TNFRSF13C (TNF receptor superfamily member 13C)
Description:
B-cell receptor specific for TNFSF13B/TALL1/BAFF/BLyS. Promotes the survival of mature B-cells and the B-cell response.
Synonyms: BAFF-R; CD268; BAFFR; BROMIX; CVID4; prolixin
Tractability: Antibody: a drug acting on it is in phase 2 or 3 trials; its Gene Ontology location is reachable by antibodies, with high confidence; UniProt predicts a signal peptide or a membrane-spanning region. PROTAC: its protein half-life has been measured.
Target class: Membrane receptor
Gene: Protein-coding gene on chromosome 22 (41,922,032 to 41,926,806, reverse strand). Ensembl gene ENSG00000159958.
Subcellular location: Membrane
Pathways (Reactome):
Immune System: TNF receptor superfamily (TNFSF) members mediating non-canonical NF-kB pathway; TNFR2 non-canonical NF-kB pathway
Gene Ontology:
Molecular function: signaling receptor activity
Biological process: B cell costimulation; positive regulation of B cell proliferation; positive regulation of T cell proliferation; T cell costimulation; tumor necrosis factor-mediated signaling pathway
Cellular component: external side of plasma membrane; plasma membrane; membrane
Genetic constraint (gnomAD): Loss-of-function variants: 8 observed, 9.2 expected, observed/expected ratio (o/e) 0.87, 90% interval 0.51 to 1.55. That is too few expected variants to judge how well the gene tolerates losing a copy. Missense variants: 260 observed, 212.28 expected, observed/expected ratio (o/e) 1.22, 90% interval 1.11 to 1.36. Synonymous variants: 157 observed, 110.06 expected, observed/expected ratio (o/e) 1.43, 90% interval 1.25 to 1.63.
Gene-disease validity (ClinGen):
ClinGen rates the evidence that TNFRSF13C causes each of these diseases.
immunodeficiency, common variable, 4 (autosomal recessive): Limited.
Homologues: Orthologues: chimpanzee TNFRSF13C (99% identical), macaque TNFRSF13C (97% identical), dog TNFRSF13C (73% identical), pig TNFRSF13C (73% identical), guinea pig TNFRSF13C (66% identical), rat Tnfrsf13c (52% identical), mouse Tnfrsf13c (51% identical). Paralogues in human: TNFRSF17 (22% identical).
Diseases named in the same sentence as TNFRSF13C in open-access papers:
TNFRSF13C is named in the same sentence as 154 diseases in open-access papers, as found by Europe PMC text mining. Sharing a sentence is not in itself a finding about the gene and the disease. The quoted sentences say what the papers report.
lymphoma (23 papers, 2012 to 2025). A malignant (clonal) proliferation of B- lymphocytes or T- lymphocytes which involves the lymph nodes, bone marrow and/or extranodal sites. "Also, NF-κB2 was upregulated in B cells from SS patients with lymphoma who harbored a missense mutation in the TNFRSF13C (BAFF-R) gene." (PMID 32201227, 2020). "Differentially regulated genes were enriched for classical lymphoma driver genes downstream of the BCR, including MALT1 and CARD11, as well as NFATC2, TNFRSF13C (BAFF), and components of the NF-κB (RELB, IRAK1, BCL3, and TNFRSF1B) pathway." (PMID 39082968, 2024).
myeloma (18 papers, 2009 to 2025). "Another receptor, TNFRSF13C, mainly expressed in B cells, is correlated with the non-MM situation and indicates the irrelevance of TNFRSF13C for myeloma cells." (PMID 34150664, 2021).
autoimmune disease (16 papers, 2009 to 2025). A disorder resulting from loss of function or tissue destruction of an organ or multiple organs, arising from humoral or cellular immune responses of the individual to their own tissue constituents. "Lastly, the TNFRSF13C (BAFF) gene regulates insulin sensitivity and is associated with autoimmune diseases." (PMID 33472578, 2021). "Earlier studies showed that blocking TNFSF13B/TNFRSF13C signaling may effectively treat autoimmune diseases mediated by B-cells in humans." (PMID 35432452, 2022).
breast cancer (10 papers, 2008 to 2024). A primary or metastatic malignant neoplasm involving the breast. "Pparγ1+/+ ErbB2 mammary tumors showed increased expression of specific chemokines and cytokines (Cxcl5, Cxcl19, Cxcl13, IL1b and Tnfrsf13c)." (PMID 33946495, 2021).
common variable immunodeficiency (9 papers, 2006 to 2023). "TNFRSF13C is a principal receptor required for BAFF-mediated mature B cell survival and it has been reported to be associated with common variable immunodeficiency." (PMID 28302172, 2017). "Mutations in TNFRSF members can also lead to common variable immunodeficiency (CVID): approximately 9 % of patients carry one or two variant alleles of TNFRSF13B (encoding TACI) and a few patients carry biallelic mutations of TNFRSF13C (encoding BAFF-R)." (PMID 27435189, 2016). "Finally, ALPS or ALPS-like features may also arise from the complementary effect of variants in CASP10 and in another non-FAS gene, such as CASP8 or TNFRSF13C (i.e., BAFF receptor, whose mutations are typically associated with common variable immunodeficiency, CVID)." (PMID 35059842, 2022).
non-Hodgkin lymphoma (6 papers, 2016 to 2026). Distinct from Hodgkin lymphoma both morphologically and biologically, non-Hodgkin lymphoma (NHL) is characterized by the absence of Reed-Sternberg cells, can occur at any age, and usually presents as a localized or generalized lymphadenopathy associated with fever and weight loss. "Besides, TNFRSF13C is a regulator of the peripheral B-cell population that enhances B-cell survival, which is decreased by HCV infection, and it has been related to HCV-induced B cells clonal disorders, such as mixed cryoglobulinemia and non-Hodgkin’s lymphoma." (PMID 34497613, 2021).
primary immunodeficiency (6 papers, 2014 to 2022). "The analysis of the altered pathways related to these genes showed the only significant KEGG pathway identified was “primary immunodeficiency pathway” (q-value <0.05), with three SDE genes upregulated (CD8A, CD8B, and TNFRSF13C) in HIV/HCV-f." (PMID 34497613, 2021). "An equally high overrepresentation (OVF = 20.83, q-value = 2.38 × 10−6) was determined for the “magenta” module that was enriched in genes that control primary immunodeficiency, including ADA, CD19, CD79A, IGLL1, TAP1, TAP2, TNFRSF13C, and ZAP70." (PMID 32873298, 2020). "In the current study, KEGG pathway enrichment analyses have revealed changes related to primary immunodeficiency in severe MPP patients, which involves CD79A, AICDA, CD19, and TNFRSF13C genes." (PMID 28302172, 2017).
lung carcinoma (5 papers, 2019 to 2026). "Stage III cancers had significantly higher expression of CXCL2, CD69, CCR4, and TNFRsf13c, all of which have been implicated as potential therapeutic targets in other malignancies, or in the case of CCR4, poor prognosis in lung cancer." (PMID 35881197, 2023).
cervical carcinoma (4 papers, 2022 to 2024). A carcinoma arising from either the exocervical squamous epithelium or the endocervical glandular epithelium. "For immunostimulator, SLC30A10 expression was correlated with TNFRSF25 (Spearman: ρ = 0.202, P = 0.00038), TNFSF13 (Spearman: ρ = -0.193, P = 0.000703), TNFRSF13C (Spearman: ρ = -0.209, P = 0.000245), and RAET1E (Spearman: ρ = 0.197, P = 0.000546) in cervical carcinoma." (PMID 35154468, 2022).
melanoma (4 papers, 2021 to 2026). A malignant, usually aggressive tumor composed of atypical, neoplastic melanocytes. "TNFRSF13C is expressed in HNSCC tumor-infiltrating lymphocytes, and has been identified as an inducer of regulatory T cells in melanoma." (PMID 39867897, 2024).
Sepsis (3 papers, 2024 to 2025). Sepsis is defined as life-threatening organ dysfunction caused by a dysregulated host response to infection. "The expression of some of those genes (FCRL1, TNFRSF13C, CD22, CD79A, POU2F2) continue to be upregulated during sepsis recovery stage too." (PMID 38898888, 2024).
acute lymphoblastic B leukemia (1 paper, 2019). "Analyzing BAFFR expression by acute lymphoblastic B leukemia cells we found that B-lymphoblasts from patients with common and pre-B-ALL can transcribe the BAFFR-encoding TNFRSF13C gene, resulting in substantial surface expression of the receptor." (PMID 31380267, 2019).
alcoholic liver diseases (1 paper, 2025). A disorder caused by damage to the liver parenchyma due to alcohol consumption. "For instance, Circ_1639 is upregulated in Kupffer cells of ethanol-fed mice, where it activates the NF-κB pathway and promotes proinflammatory factor production by sponging miR-122 and elevating tumor necrosis factor receptor superfamily member 13C (TNFRSF13C) expression in alcoholic liver disease." (PMID 41479922, 2025).
inflammatory bowel disease (1 paper, 2021). A spectrum of small and large bowel inflammatory diseases of unknown etiology. "In dogs suffering from inflammatory bowel disease (IBD) associated with significantly decreased levels of IgA, the expression levels of IgA were associated with the DNA methylation state of the TNFRSF13B and TNFRSF13C genes and the mRNA expression levels of TACI and BAFF-R." (PMID 33981304, 2021).
oral cancer (1 paper, 2025). "The genes PPT1 (palmitoyl-protein thioesterase 1), LILRA4 (leukocyte immunoglobulin-like receptor A4), and HCK (hemopoietic cell kinase) were correlated with a lower risk of oral cancer, while TNFRSF13C (tumor necrosis factor receptor superfamily member 13c) was linked to a higher risk." (PMID 40521000, 2025).
tumor (40 papers, 2009 to 2025). "In addition, magnesium homeostasis is also closely related to the expression of immune activation genes in tumor microenvironment, such as TNFRSF13C, BTNL2, TNFSF4 and so on, thus promoting anti-tumor immune response." (PMID 41174507, 2025). "Furthermore, eight target genes (COL4A3, FAM30A, FCRL5, MDM4, SYNE2, TNFRSF13C, TPTEP2, VAMP1) were systematically positively correlated with ESR2 expression patterns in tumor types with low ESR2 expression as a prognostic factor concerning OS or DFS." (PMID 39201394, 2024). "In other words, CD27, EDA, TNF, TNFRSF12A, TNFRSF13C, and TNFRSF9 expression may also affect the immunotherapy effect on tumours by regulating the expression of immune checkpoint molecules in the tumour microenvironment." (PMID 35392242, 2022). "Notably, our findings highlight seven genes (FAM30A, MDM4, POU2AF1, SYNE2, TNFRSF13C, TPTEP2, VAMP1) presenting positive correlations with ESR2 expression patterns in all tumor types with high ESR2 expression as a positive prognostic factor with regard to OS or DFS." (PMID 39201394, 2024). "Therefore, we hypothesised that CD27, EDA, TNF, TNFRSF12A, TNFRSF13C, and TNFRSF9 may affect tumour prognosis mainly by regulating the TGF-β signaling pathway." (PMID 35392242, 2022). "While lymphoid aggregates alone did not distinguish between responsive and non-responsive tumours, the integrated analysis revealed higher expression of genes like CD37, MS4A1, BLK, CD79A/B, and TNFRSF13C in responsive tumours’ lymphoid aggregates." (PMID 40141092, 2025). "Finally, we investigated genes displaying similar expression patterns as ESR2 in tumor tissues, identifying potential co-expressed genes that may exert a synergistic effect on clinical outcomes, with significant results, including the expression of ACIN1, SYNE2, TNFRSF13C, and MDM4." (PMID 39201394, 2024).
cancer (29 papers, 2009 to 2025). A tumor composed of atypical neoplastic, often pleomorphic cells that invade other tissues. "Other candidates, such as CD79B, MAP4K1, GRAP, TNFRSF13C, and INA, had comparable scores and are candidates for further study, as they have also been implicated in carcinogenesis of other cancer types." (PMID 28146432, 2017). "The qRT-PCR results of the clinical samples also showed that the mRNA expression of CD27, TNF, TNFRSF12A, TNFRSF13C, and TNFRSF9 is upregulated in cancer tissues, except EDA whose mRNA expression is downregulated in cancer tissues." (PMID 35392242, 2022).
infection (16 papers, 2008 to 2025). The state of being infected such as from the introduction of a foreign agent such as serum, vaccine, antigenic substance or organism. "Meanwhile, the mRNA expression of TNFRSF13C was down-regulated and the protein expression was up-regulated in the 72 h infection group." (PMID 36496794, 2022). "Independent of the genotype, infection with H. felis, resulted in downregulation of several genes, such as CXCL5 and TNFRSF13c (infected versus uninfected mice)." (PMID 26966907, 2016).
blood cancers (1 paper, 2024). "Among the proteins associated with risk of haematological cancers, we identified associations with risk of multiple blood cancers for members of the FC-receptor protein [FCRL1, FCRL2, FCRL3, FCRL5, FCRLB] and TNF receptor families [TNFRSF4, TNFRSF9, TNFRSF13B, TNFRSF13C, TNFSF13B, TNFSF13]." (PMID 38750076, 2024).
TNFRSF13C also shares sentences with these, for which no sentence is quoted: lupus (28 papers); atherosclerosis (16); B-cell lymphoma (13); Autoimmunity (12); rheumatoid arthritis (9); multiple myeloma (8); leukemia (6); follicular lymphoma (5); malaria (5); chronic lymphocytic leukemia (4); diffuse large B-cell lymphoma (4); glioma (4); Hypertension (4); Immunodeficiency (4); lupus nephritis (4); mantle cell lymphoma (4); multiple sclerosis (4); primary Sjögren’s syndrome (4); viral infection (4); acute lymphoblastic leukemia (3); antibody deficiencies (3); Burkitt lymphoma (3); hematological malignancies (3); Hepatic steatosis (3); IgA nephropathy (3); influenza (3); myasthenia gravis (3); acute kidney injury (2); Arthritis (2); chronic graft versus host disease (2).
A further 105 diseases each share a sentence with TNFRSF13C in 2 papers or fewer.